HIF1A (hypoxia inducible factor 1 subunit alpha)
Diseases named in the same sentence as HIF1A in open-access papers (continued):
Sharing a sentence is not in itself a finding about the gene and the disease.
tumor (continued). "Subsequently, we verified that TEAD1, a transcriptional coactivator of Yes-associated protein 1 (YAP1), directly bound to the HIF1A promoter region and the YAP1 and TEAD1 proteins co-regulated the expression of HIF1A, thus promoting tumour glycolysis." (PMID 33218358, 2020). "Under hypoxic conditions PD-L1 expression was directly induced by HIF-1α on MDSCs in B16-F10 tumor-bearing mice, and PD-L1 blockade increased MDSC-mediated T cell activation by downregulating IL-10 and IL-6 expression." (PMID 33193345, 2020). "Further, exosomal miR-21 levels correlated with T stage and lymph node metastasis as well as with the tumor HIF-1α/2α expression, reflecting the hypoxic status of the tumor." (PMID 32517240, 2020). "It is established that the endothelial response to tumor hypoxia signaling is the angiogenic switch involving HIF-1α stabilization and transcription, along with production of VEGFs, angiopoietin 2, IL-8, and other factors." (PMID 33552076, 2020). "The effect of charged particle irradiation on the molecular pathways affected by tumor hypoxia, specifically HIF1-α expression, is underexplored." (PMID 32117774, 2020). "A link between miRNA regulating HIF-1α expression via PI3K/Akt signaling was shown in other tumor models as well." (PMID 32707933, 2020). "First, tumour-feeding arteries are embolised by TACE treatment, inevitably giving rise to the elevation of the HIF-1α level that is related to tumour recurrence, disease progression and distant metastasis." (PMID 32917226, 2020). "Our results are consistent with those of previous in vitro studies of tumor tissues showing that chrysin inhibits VEGF gene transcription by inhibiting HIF-1α expression." (PMID 32325771, 2020). "IHC staining with ki-67, PKM2 and HIF-1α of xenograft tissues was in favor of AC020978's role in mediating tumor growth and glycolysis." (PMID 32308748, 2020). "While the data were compelling, they stood in contrast with the well-established tumor-promoting properties of HIF1α in other malignancies (via angiogenesis, metabolic adaptation, resistance, etc.)." (PMID 33077781, 2020). "HIF-1α is also involved in decreasing the anti-tumor immune response via its control of the PD-1/PD-L1 in immune cells and tumor cells." (PMID 33256070, 2020). "Growing evidence indicates that tumor metabolic reprogramming driven by hypoxia also participates in angiogenesis via HIF-1α independent pathway." (PMID 32751958, 2020). "It is admitted that the adaptation of tumor cells to the hypoxic microenvironment is regulated by HIF-1a, which is considered an independent biomarker of response to hypoxia." (PMID 32766135, 2020). "Hypoxia‐inducible factor 1 (HIF‐1α) is expressed in response to hypoxia and contributes to tumor progression and metastasis." (PMID 32436609, 2020). "Spearman’s rank correlation analysis revealed a positive correlation for TBRmax (rho 0.78, p < 0.01) and TBRpeak (rho 0.79, p < 0.0001) with the number of HIF1α positively stained nuclei on the histological tumor slides." (PMID 33105540, 2020). "Hypoxia has long been identified to co-exist with chronic inflammation in tumors and HIF-1α, a master regulator of tumor hypoxia, is known to be regulated in NFкB dependent manner and cooperatively maintain malignant phenotypes in cancer." (PMID 31992226, 2020). "Herein, hypoxic conditions induce hypoxia-inducible factor 1 α (HIF-1α) to provide crucial biological processes needed for survival and progression of tumor cells such as angiogenesis." (PMID 33072180, 2020). "In normal oxygen conditions, HIF-1α is degraded by a tumor suppressor, the von Hippel-Lindau suppressor." (PMID 32377312, 2020). "In previous studies, it was found that HIF-1α was notably stabilized in malignant tumor cells under hypoxic conditions, along with upregulating its target gene, VEGFA, which is considered the principal inducer of angiogenesis." (PMID 32273947, 2020).
tumor (continued). "To corroborate the transcriptional analysis, we evaluated the protein levels of total and phosphorylated AMPK (pAMPK), as well as HIF-1α in tumor and fibroblast cells cultured under the analyzed conditions after 48 h incubation." (PMID 32596143, 2020). "Taken together, these results indicate that inhibition of NOS activity is likely to be responsible for reduced HIF1α activity and hence tumor suppression by CAV1." (PMID 32825247, 2020). "For the first time, we demonstrated the effect of propranolol on CA IX and HIF-1α levels in a 3D multicellular model simulating a more faithful tumour mass and relations in the tumour." (PMID 33228233, 2020). "The result showed a decreasing trend of ABCG2 and HIF‐1α in the aspirin and aspirin with cisplatin groups, which was consistent with the lightening of H460R tumor stemness, invasion and metastasis." (PMID 32991066, 2020). "In hypoxic tumor cells, hypoxia-inducible factor 1α (HIF-1α) accumulates as an adaptive response to hypoxia." (PMID 32367141, 2020). "The fragmentation phenomenon has been defined as the appearance of separate fibroblast-like cells with nuclear expression of HIF-1α and Snail in the tumor solid component." (PMID 32849870, 2020). "The relevance of the HIF1-α/Ku80/PDK1 pathway to alterations in metabolism of other cells in the tumour microenvironment will be important to determine." (PMID 33375613, 2020). "HCC tissues were further divided into FABP5-high or HIF-1α-high and FABP5-low or HIF-1α-low tissues; we found that elevated FABP5 and HIF-1α expression in the tumor was associated with poor tumor-free survival in HCC patients." (PMID 33128030, 2020). "The activation of mTOR, an important downstream target of AKT, can promote angiogenesis by increasing VEGF expression or inducing HIF-1α-dependent gene expression in tumor cells." (PMID 33116125, 2020). "The results showed that alkaline microenvironment inhibited the viability and invasion of GC cells and the expression of mTOR, AKT, Wnt, Glut, and HIF-1α genes and proteins, promoted tumor cell apoptosis, and inhibited GC progression." (PMID 32211041, 2020). "Hypoxia-inducible factor-1α (HIF-1α) plays a critical role in promoting tumor angiogenesis by activating the transcription of major proangiogenic factors, including VEGF." (PMID 32751120, 2020). "Increased expression of HIF1A protein in tumor tissues can be achieved by enhancing transcription and/or mRNA translation, or by decreasing proteasomal degradation." (PMID 32894161, 2020). "It shows that down-regulation of HIF-1α mediated by miRNA-181c results in the inhibition of hypoxia-induced metabolic alterations within tumor cells with NRF2-silencing." (PMID 33109235, 2020). "Tumor region of HCC tissue from HCC patients with high FDG uptake showed statistically significantly more positive regions of Hif1α expression and membranous GLUT1 as compared with HCC with low FDG uptake by immunostaining." (PMID 32001727, 2020). "Following phosphorylation by GSK3β, HIF-1α ubiquitination via FBXW7 is increased, which promotes proteolysis of HIF-1α and inhibits tumor growth." (PMID 33004065, 2020). "HIF-1α is likely to have a pivotal role in the ‘pro-tumor’ effect of ET-1 and elevated levels of HIF-1α are strongly correlated with metastasis, angiogenesis, cancer resistance and poor prognosis." (PMID 32197449, 2020). "Some studies showed that hypoxia-activated HIF-1α upregulates PD-L1 expression on tumor cells and immune cells by binding directly to a hypoxia response element in the proximal promoter of CD274 (encoding PD-L1)." (PMID 32775303, 2020). "Tumor hypoxia through HIF-1α regulation drives genetic instability in a large group of genes that determine malignant and aggressive molecular features." (PMID 32751958, 2020). "HIF-1α expression in the tumour parenchyma was high and was detected in both the nucleus and cytoplasm, whereas the stroma showed a low staining intensity." (PMID 32386517, 2020).
tumor (continued). "Adenocarcinoma- derived SKOV3 line which forms clear cell tumours in vivo displayed acute induction of HIF-1α mRNA after 4 h, which returned rapidly to a similar level to cells grown under normoxic conditions." (PMID 33143089, 2020). "This depends on a reduced intake of oxygen and nutrients due to inadequate vascularization and diffusion during tumor growth, which, through stabilization of the hypoxia-inducible transcription factor HIF-1α, shifts the cell metabolism toward glycolysis." (PMID 32560326, 2020). "Together, these results reveal an important role of Nrf2 in the regulation of HIF-1α protein levels under hypoxia and suggest a novel mechanism for cisplatin-resistance in the tumor micro-environment." (PMID 33290263, 2020). "HIFs are broadly expressed in human cancer cells and HIF1α and HIF2α were previously suspected of promoting tumor progression through overlapping functions." (PMID 32847073, 2020). "HIF1-α, which is also overexpressed in tumor cells, increases the transcription of genes regulating glucose transport and glycolytic enzymes." (PMID 33153193, 2020). "In tumors, hypoxia can develop within the tumor mass to activate HIF1α because of impaired vascularization." (PMID 33033473, 2020). "On the other hand, the inhibition of β2-AR signalling by β2 selective antagonist ICI118551 or knockdown of β2-AR expression, led to enhanced autophagy, HIF1α destabilization and tumour growth suppression." (PMID 33228233, 2020). "Vorinostat inhibits HIF-1α, which results in inhibition of angiogenesis and upregulation of microRNAs (miRs), which act as tumor suppressors." (PMID 32018226, 2020). "The best characterised tumour suppressor function of pVHL relates to its role in targeting the alpha subunits of the hypoxia-inducible transcription factors (HIF-1α and HIF-2α) for oxygen-dependent, ubiquitin-mediated proteolytic degradation." (PMID 32807776, 2020). "To find any correlation between miRNA expression and HIF-1α expression in tumor tissues, we conducted a Pearson correlation coefficient analysis." (PMID 32707933, 2020). "HIF-1α promotes tumor cell growth, migration, and invasion in OS through activation of the AKT/cyclin D1 signal cascade." (PMID 33425993, 2020). "The HIF-1α activity enables hypoxic tissue to adopt an aggressive phenotype characterised by angiogenesis and even metastasis, thus, contributing to tumour progression, metabolic changes, cell proliferation, and the activation of signalling pathways." (PMID 32386517, 2020). "TAMs also upregulate HIF1α and shift to glycolysis because of the hypoxic environment in the tumor, and HIF1α induces NO production by TAMs." (PMID 32518979, 2020). "PTEN is also a tumor suppressor that downregulates the expression of HIF-1α and regulates the PI3K/Akt pathway." (PMID 32707933, 2020). "These are usually recruited by HIF1a and tumor-secreted chemokines such as ANG2 in the setting of anti-angiogenic therapy." (PMID 32175278, 2020). "In subsequent stages, HIF1A plays a role to maintain this rapid proliferation rate to modulate tumor progression in later stages." (PMID 32212787, 2020). "There is evidence for correlations between prognosis and biomarkers with poor tumor oxygenation such as HIF-1α, GLUT-1 and lactate." (PMID 31906998, 2020). "In this review, we briefly elucidate the reciprocal regulation between HIF-1α and ncRNAs in terms of transcription, translation, and protein stability, as well as their effect on the various biological behaviors of tumor cells." (PMID 32014012, 2020). "ACF has been identified as an efficient inhibitor of HIF-1α dimerization and consequently has potent inhibitory effects on tumor growth and vascularization." (PMID 33396270, 2020). "More experiments and analyses are required to elucidate how HIF pathway affect tumor immune microenvironment as HIF1A is an incredibly promising target for cancer therapy." (PMID 32457841, 2020).
tumor (continued). "TAMs also up-regulate expression of Programmed death-ligand 1 (PD-L1), under the influence of HIF1α, leading to suppression of T cell activity in hypoxic tumor regions." (PMID 32983125, 2020). "Especially HIF-1α expression has been shown to be positively correlated with poor prognosis, tumor grade, metastasis and lower overall survival rate." (PMID 33400730, 2020). "In this context HIF1α can repress tumor cell proliferation in different biological settings, including that of ccRCC, while HIF2α favors the proliferation of VHL-deficient RCCs and tumor formation." (PMID 33321829, 2020). "Activation of the HIF-1α transcription factor induces the generation of angiogenic factors to stimulate the growth of new blood vessels, providing nutrients for the tumor cells and allowing their survival in the hypoxic microenvironment." (PMID 33456484, 2020). "In many types of cancers, Parkin expression is frequently down regulated and therefore stabilizes HIF-1α and promotes tumor metastasis and cancer development." (PMID 33519361, 2020). "In the previous reports, the relationship of HDAC4 and Hif1α was investigated in cancer cell lines or for tumor angiogenesis." (PMID 32354322, 2020). "Mechanistically, mtCa2+ overload leads to increased mitochondrial reactive oxygen species, which activate HIF1α signaling supporting metastasis of NCLX-null tumor cells." (PMID 32914752, 2020). "Several cancer therapeutics target HIF-1α/VEGF pathway alone or in combination with other pathways to alleviate tumor angiogenesis and permeability." (PMID 32529267, 2020). "Through Western blotting, it also confirmed that LNT not only reduced the levels of VEGF and HIF-1α in tumor tissues, but also inhibited the activity of Akt and mTOR." (PMID 33245358, 2020). "HIF-1α is a key transcriptional regulator that mediates the adaptation of cells to hypoxic microenvironment and plays an important role in tumor cell energy metabolism, growth invasion, and angiogenesis." (PMID 32211041, 2020). "HIF-1α participates in several specific processes resulting in tumour vascularization and reoxygenation." (PMID 33008040, 2020). "IHC analysis showed that Ki67 and HIF-1α positive staining were also decreased in sh-MIR210HG tumor tissues compared with that in sh-Ctrl group." (PMID 33392077, 2020). "IHC staining assay exhibited that HIF-1α protein located in both cytoplasm and nucleus of tumor cells." (PMID 31942180, 2020). "HIF-1α plays a crucial role in the adaptive responses to hypoxia of tumor cells through transcriptional activation of downstream genes required for tumor survival and progression, including those for angiogenesis." (PMID 33489901, 2020). "In hypoxic tumour cells, HIF-1α can induce the full expression of LDHA, which promotes the conversion of pyruvate to lactic acid and ensures the continuous production of NAD+." (PMID 32928258, 2020). "Upregulated GLUT1 induced by HIF‐1α has been reported to increase cellular uptake of glucose and enhance aerobic glycolysis in tumor cells." (PMID 32533646, 2020). "Conversely, SIRT3 and SIRT6 also act as tumor suppressors, restricting aerobic glycolysis in cancer cells through destabilization of hypoxia inducible factor 1 subunit alpha (HIF-1α) and inhibition of glycolytic kinases, respectively." (PMID 33117804, 2020). "Analysis of tumor lysates showed reduced amounts of inflammatory and pro-angiogenic factors in HIF-1α-KD tumors, such as Cyr61 or Dll4, which correlated with a normalized vasculature." (PMID 33142239, 2020). "Long-term administration of AIs up-regulates HIF-1α and induces hypoxia in the tumor microenvironment by over-pruning blood vessels." (PMID 32175278, 2020).
tumor (continued). "Digoxin, with preclinical success for the inhibition of HIF-1α and delay of tumor growth, is now in phase II of clinical trials (NCT01763931)." (PMID 33266219, 2020). "The results indicate that PIC–BSA NPs are effective against the downregulation of HIF-1α that leads to the reduction in proliferation, migration, and invasion of the tumor." (PMID 31906321, 2020). "Previous studies showed that HIF-1α is involved in MVs and exosome biogenesis in different cell lines such as tumor and non-tumor cells." (PMID 33302971, 2020). "Overactivated HER2 signaling results in increased HIF-1α and VEGF expression, which in turn activate the downstream kinase FKBP-rapamycin-associated protein (FRAP), therefore contributing to tumor progression by mediating angiogenesis and metabolic adaptation." (PMID 33489906, 2020). "NKG2D interacts with its ligand for immune surveillance and lysis of tumor cells, and this process is regulated by HIF-1α." (PMID 32587480, 2020). "It has been demonstrated that CAIX expression in tumor cells is regulated by HIF-1α transcription factor under hypoxic conditions." (PMID 32823915, 2020). "One study showed that HIF-1α-dependent expression of CD47 leads to decreased phagocytosis of tumor cells, which promotes cancer progression and immune evasion." (PMID 32775303, 2020). "Tumour microenvironment hypoxia is a major driver of adenosine production, via the upregulation of hypoxia-inducible factor (HIF)-1α." (PMID 33375613, 2020). "For example, PKM2 promotes tumor growth and suppresses cell apoptosis through regulating Bcl-xL transcription in gastric cancer cells or regulating NF-κB/p65 and HIF-1α activation and mitogen-activated protein kinases (MAPKs) in pancreatic tumor cells." (PMID 33292198, 2020). "Among proangiogenic factors, vascular endothelial growth factor (VEGF), a sub-family of growth factors which is induced under hypoxic conditions through hypoxia-inducible factor (HIF)-1α promotor binding, plays a pivotal role in tumor angiogenesis." (PMID 33352897, 2020). "In an interesting study, Krzywinska and colleagues demonstrated that HIF-1α depletion impairs NK cell function and tumor growth." (PMID 32316260, 2020). "HIF-1α is a key transcription regulating molecule that mediates the adaptive response of tumor cells to the hypoxic microenvironment." (PMID 32626535, 2020). "Our previous study found that HPV-16 E7 oncoprotein enhanced HIF-1α/VEGF- mediated tumor angiogenesis in NSCLC cells." (PMID 32792865, 2020). "Previous evidence has demonstrated that hypoxia promotes the growth, glycolysis and stem cell potential of various tumours through the YAP/HIF1A signalling pathway." (PMID 33218358, 2020). "HIF-1α (hypoxia inducible factor-1 alpha) is a key regulator of cancer cell proliferation that is activated in response to the hypoxic tumour microenvironment, to initiate the metabolic switch in cancer cells from oxidative phosphorylation to glycolysis." (PMID 32878019, 2020). "There are few antitumor agents that target HIF-1α in ascites tumor cells in in-vivo have been reported." (PMID 33400732, 2020). "HIF-1a drives the differentiation of myeloid-derived suppressor cells (MDSCs) to immunosuppressive TAMs, whereas MDSCs in the TME are also responsible for tumor-associated antigen-specific T cell tolerance." (PMID 32069809, 2020). "Visual analysis indicated that the number of tumour metastases were significantly reversed by HIF-1α rescue." (PMID 31857720, 2020). "Numerous lines of evidence argue that HIF-2α plays a major pro-tumourigenic role in established human ccRCCs, whereas HIF-1α appears to function rather to inhibit aggressive tumour behaviour." (PMID 32807776, 2020). "As the indicator and product of hypoxia environment, the expression of HIF-1α increase the extravasation of cancer cell and recruitment of circulating tumor cell." (PMID 32047565, 2020).